TRBV18 (T cell receptor beta variable 18)
Description:
V region of the variable domain of T cell receptor (TR) beta chain that participates in the antigen recognition. Alpha-beta T cell receptors are antigen specific receptors which are essential to the immune response and are present on the cell surface of T lymphocytes. Recognize peptide-major histocompatibility (MH) (pMH) complexes that are displayed by antigen presenting cells (APC), a prerequisite for efficient T cell adaptive immunity against pathogens. Binding of alpha-beta TR to pMH complex initiates TR-CD3 clustering on the cell surface and intracellular activation of LCK that phosphorylates the ITAM motifs of CD3G, CD3D, CD3E and CD247 enabling the recruitment of ZAP70. In turn ZAP70 phosphorylates LAT, which recruits numerous signaling molecules to form the LAT signalosome. The LAT signalosome propagates signal branching to three major signaling pathways, the calcium, the mitogen-activated protein kinase (MAPK) kinase and the nuclear factor NF-kappa-B (NF-kB) pathways, leading to the mobilization of transcription factors that are critical for gene expression and essential for T cell growth and differentiation. The T cell repertoire is generated in the thymus, by V-(D)-J rearrangement. This repertoire is then shaped by intrathymic selection events to generate a peripheral T cell pool of self-MH restricted, non-autoaggressive T cells. Post-thymic interaction of alpha-beta TR with the pMH complexes shapes TR structural and functional avidity.
Synonyms: TCRBV18S1
Gene: T-cell receptor variable (V) gene on chromosome 7 (142,615,716 to 142,616,415, forward strand). Ensembl gene ENSG00000276557.
Subcellular location: Cell membrane
Gene Ontology:
Biological process: cell surface receptor signaling pathway
Cellular component: plasma membrane
Homologues: Orthologues: dog TRBV18 (68% identical). Paralogues in human: TRBV12-5 (51% identical), TRBV16 (49% identical), TRBV7-3 (49% identical), TRBV11-1 (48% identical), TRBV12-3 (48% identical), TRBV12-4 (48% identical), TRBV17 (48% identical), TRBV7-1 (48% identical), TRBV7-6 (48% identical), TRBV7-9 (48% identical), TRBV7-2 (47% identical), TRBV7-4 (47% identical), and 39 more.
Diseases named in the same sentence as TRBV18 in open-access papers:
TRBV18 is named in the same sentence as 4 diseases in open-access papers, as found by Europe PMC text mining. Sharing a sentence is not in itself a finding about the gene and the disease. The quoted sentences say what the papers report.
lung carcinoma (1 paper, 2022). "TRBV18 was detected more abundantly in tumor tissues than in adjacent non-tumor tissues of lung cancer." (PMID 35371059, 2022).
cancer (2 papers, 2019 to 2022). A tumor composed of atypical neoplastic, often pleomorphic cells that invade other tissues. "In our study, TRBV20-1 and TRBV18 were identified as differentially enriched gene segments between cancer tissues and normal lung tissues." (PMID 31479759, 2019). "We also compared the TRBV and TRBJ gene usage frequency between cancer tissues and normal lung tissues and found that TRBV20-1 and TRBV18 were used more frequently in cancer tissues than in normal lung tissues." (PMID 31479759, 2019).
tumor (2 papers, 2022). "The tumor group has a significantly lower gene usage of TRBV30, TRBV12-4, TRBV4-1, TRBV4-2, TRBV18, TRBJ1-1, TRBJ1-5, and TRBJ2-2." (PMID 35967453, 2022). "In abundance heatmap result, we can find that the usage pattern of Vβ genes in peripheral blood such as TRBV18, etc., are seemingly distinguished from tumor and adjacent non-tumor tissues." (PMID 35371059, 2022).
TRBV18 also shares sentences with these, for which no sentence is quoted: ulcerative colitis (1 paper).